HDGF (heparin binding growth factor)
Diseases named in the same sentence as HDGF in open-access papers (continued):
Sharing a sentence is not in itself a finding about the gene and the disease.
glioma (continued). "In glioma and ovarian cancers, NAP1L1, via its interaction with HDGF, activated c-Jun, an oncogenic transcription factor, to induce CCND1/CDK4/CDK6 expression resulting in cellular proliferation and chemoresistance to cisplatin." (PMID 40176914, 2025). "Hepatoma-derived growth factor (HDGF) is an acidic heparin-binding protein with mitogenic and angiogenic functions, whose expression level in gliomas is positively correlated with the degree of malignancy." (PMID 35874843, 2022). "To verify the functions of NAP1L1 and HDGF, we analyzed the correlation of NAP1L1 and HDGF expressions with widely recognized clinicopathological parameters in glioma specimens." (PMID 34959221, 2021). "In human glioma cell lines U251 and LN229, HDGF forms a complex with β-catenin promoting tumor growth and metastasis." (PMID 34680593, 2021). "We also found that the expression of HDGF was positively correlated with the tumor WHO grade, as shown by the dramatical differences between high- and low-grade glioma patients." (PMID 34959221, 2021). "To further evaluate the relationship between HDGF and NAP1L1, we performed MTT and EdU assays using NAP1L1-overexpressing glioma cells upon HDGF knockdown." (PMID 34959221, 2021). "Glioma patients having high expression of both NAP1L1 and HDGF showed the worst survival prognoses as compared to other groups." (PMID 34959221, 2021). "Subsequently, we transfected si-HDGF and si-control in A172 and SHG44 cells to explore the influence of HDGF on glioma cell proliferation, apoptosis, migration, and invasion." (PMID 33817254, 2020). "For example, by sponging miR-15a/b-5p to upregulate the expression of HDGF and activating the Wnt/β-catenin signaling pathway, AGAP2-AS1 could promote the proliferation of glioma cells." (PMID 33889541, 2021). "Essentially, miR-384 inhibitor abolished the suppression of SNHG3 silencing on HDGF mRNA and protein expression, validating that SNHG3 accelerates cell progression and induces apoptosis by upregulating HDGF expression via sponging miR-384 in glioma." (PMID 33817254, 2020).
endometrial cancer (14 papers, 2014 to 2022). Primary or metastatic malignant neoplasm involving the endometrium (mucous membrane that lines the endometrial cavity). "However, in endometrial cancer, HDGF has been implicated in multiple abnormalities." (PMID 33292199, 2020). "Prior investigation performed by our group using mass spectrometry (unpublished data) had determined that NAP1L1 was a potential candidate interaction protein of HDGF in endometrial carcinoma." (PMID 35351053, 2022). "It has been recently reported that ZEB1 (Zinc finger E-box binding homeobox 1) can bind to the HDGF (hepatoma-derived growth factor) promoter to stimulate HDGF transcription in EC (endometrial carcinoma) cells." (PMID 35000617, 2022). "ZEB1 can bind to the promoter of the liver cancer-derived growth factor (HDGF) and increase the level of HDGF transcription, leading to the pathogenesis of endometrial cancer (EC)." (PMID 34676171, 2021). "In endometrial cancer, miR-873-5p exerts a tumor-suppressor role via directly targeting hepatoma−derived growth factor (HDGF)." (PMID 34497766, 2021). "In our preliminary work, using mass spectrometry, we predicted a direct interaction between NAP1L1 and HDGF proteins, and this was confirmed in endometrial carcinoma (unpublished data)." (PMID 34959221, 2021). "Prior investigation from our group using mass spectrometry combined with exogenous co-IP, indicated that HDGF was a potential interacting partner of NAP1L1 in endometrial carcinoma (unpublished data)." (PMID 34959221, 2021). "Due to the limited sample size of patients in our study, further investigations are needed to confirm these findings and establish the role of HDGF as a reliable clinical predictor for endometrial carcinoma outcome." (PMID 24692842, 2014). "Interestingly, previous studies in our lab had found that NAP1L1 is a potential candidate of HDGF interaction proteins in endometrial carcinoma using exogenous Co-IP assay combined with mass spectrometry (unpublished data)." (PMID 34368121, 2021). "Interestingly, a previous study in our group had found that NAP1L1 is a potential candidate of HDGF interaction proteins in endometrial carcinoma using exogenous Co-IP combined with mass spectrometry (unpublished data)." (PMID 34368121, 2021). "Expression of hepatoma-derived growth factor (HDGF) and DDX5 were positively correlated in endometrial cancer (EC) tissues." (PMID 35954483, 2022). "Correlation between the clinicopathological factors and the expression of HDGF and DDX5 in endometrial cancer." (PMID 31032220, 2019). "Hepatoma-derived growth factor (HDGF) interacts with DDX5 to induce β-catenin expression and stimulate its nuclear translocation by activating the PI3K/AKT signaling pathway to promote carcinogenesis of endometrial cancer." (PMID 35992805, 2022). "In this study, Xiao, a member of our group, carried out an Co-IP assay combined with mass spectrometry to search the potential interaction factors of HDGF in endometrial carcinoma (data not shown." (PMID 34774047, 2021). "Correlation between HDGF and DDX5 expression in endometrial cancer tissues." (PMID 31032220, 2019). "Thus far, no study has examined the role of HDGF in endometrial carcinoma." (PMID 24692842, 2014).
liver cancer (14 papers, 2010 to 2025). An epithelial or non-epithelial malignant neoplasm that arises from the liver. "Hepatoma-derived growth factor (HDGF), a heparin-binding protein isolated from the conditioned medium of the liver cancer-derived cell line HUH-7, is present in various tissues, including the liver, intestines, retina, kidneys, and spinal cord." (PMID 40001585, 2025). "Studies have shown that MKLN1-AS acts as a miR-654-3p sponge competing with HDGF to play a pro-cancer role in liver cancer progression." (PMID 37426702, 2023). "HDGF, which belongs to an eponymous family of proteins, is a heparin binding growth factor originally identified from the conditioned medium of human liver cancer cell line Huh-7." (PMID 35351053, 2022). "Hepatoma-derived growth factor (HDGF) was regarded as an independent prognostic factor in liver cancer and was significantly upregulated in HCC." (PMID 34046411, 2021). "Furthermore, we showed a significant correlation of high HDGF expression levels with a shorter overall survival of HCC patients offering potential prognostic value for HDGF in liver cancer." (PMID 35578240, 2022). "Therefore, the post-transcriptional regulation of EIF2S1 and HDGF plays a key role in the progression of liver cancer patients." (PMID 34094926, 2021). "In HCC, HDGF is considered a liver cancer-derived growth factor and it has been shown that targeted inhibition of HDGF may have efficacy as a new type of HCC treatment." (PMID 34094926, 2021). "The phosphodiesterase activity of Prune may be well suited to the development of small molecule inhibitors, whilst antibodies to HDGF may be useful in the treatment of colorectal and liver cancer where it has been shown to act as an extracellular mitogen." (PMID 26643252, 2015). "Similarly, in liver cancer, MIAT interacts with miR-520d-3p and miR-214, affecting EPHA2 and hepatoma-derived growth factor (HDGF) expression, respectively." (PMID 37624039, 2023). "A significant increase of HDGF expression in liver cancer tissue compared to adjacent non-tumorous liver tissue was observed in all four HCC datasets." (PMID 35578240, 2022).
pancreatic cancer (12 papers, 2010 to 2025). "Recently, HIF-1α has been reported that directly bound to the HDGF promoter region, which was highly correlated with pancreatic cancer-associated fibrosis under normoxic condition." (PMID 31711427, 2019). "As shown by existing evidence, HCP5 negatively regulates miR-214-5p to influence bioprocesses such as autophagy and apoptosis in pancreatic cancer via the miR-214-5p/HDGF axis." (PMID 37208635, 2023). "In addition, HDGF was suggested to be related to gemcitabine resistance in pancreatic cancer." (PMID 32545762, 2020). "Recently, HDGF was reported to be induced by transforming growth factor (TGF)-β1, and to contribute to the growth of pancreatic cancer cells through the anti-apoptotic effects on pancreatic stellate cells." (PMID 32545762, 2020). "Furthermore, anti-HDGF antibodies exhibited significant efficacy in pancreatic cancer models, with no observable toxicity across all experimental models." (PMID 41278276, 2025).
colorectal cancer (9 papers, 2015 to 2026). A primary or metastatic malignant neoplasm that affects the colon or rectum. "HDGF promotes proliferation, migration, and invasion in colorectal cancer, prostate cancer, and bladder cancer." (PMID 41278276, 2025). "The knockdown of HDGF was reported to activate the mitochondrial apoptotic pathway, and a recent study revealed the involvement of HDGF in the proliferation and invasion of colorectal cancer cells." (PMID 32545762, 2020). "The expression of HDGF is observed in human colorectal cancers, and HDGF has been shown to stimulate the proliferation of colorectal cancer cells." (PMID 32545762, 2020). "In light of these findings, HDGF is considered to play an important role in gut epithelial cell proliferation, including the proliferation of colorectal cancer cells." (PMID 32545762, 2020). "In colorectal cancer cells, the overexpression of HDGF inhibits drug-induced apoptosis, and HDGF knockdown induces apoptosis through the mitochondrial pathway, suggesting that HDGF is involved in the process of cancer cell resistance to chemotherapy." (PMID 26101867, 2015). "Similarly, in colorectal cancer, Mettl3 drives tumor progression by sustaining HDGF expression and promoting glycolysis." (PMID 41517663, 2026). "The inhibition of HDGF induced apoptosis in colorectal cancer cells." (PMID 32545762, 2020).
melanoma (9 papers, 2002 to 2023). A malignant, usually aggressive tumor composed of atypical, neoplastic melanocytes. "Therefore, targeting HDGF may well be a novel strategy for the treatment of melanoma and also be used as a diagnostic marker for melanoma." (PMID 23536873, 2013). "By analyzing clinical samples from melanoma patients with different grades of stemness, we noted that HDGF and LGR5 correlated with the expression of a commonly used CSC marker, CD133, which was co-localized in the microvascular regions of melanoma tissues." (PMID 34106558, 2021). "Based on these findings, we set out to investigate the influences of HDGF expression on tumor progression of melanoma cells in vitro and in vivo." (PMID 23536873, 2013). "It was found that HDGF-treated melanoma cells showed a significant elevation in the extent of cell invasion compared to untreated or Ad-GFP control groups (P<0.05)." (PMID 23536873, 2013). "In contrast, the tumor burden of melanoma from Ad-HDGF shRNA-infected cells was significantly attenuated." (PMID 23536873, 2013). "E-cadherin promoter analysis also confirmed that exogenous HDGF application reduced the promoter activity of E-cadherin in B16–F10 melanoma cells." (PMID 23536873, 2013). "We then examined the efficacy of HDGF overexpression for promoting lung metastasis in mice inoculated with B16–F10 melanoma cells for 14 days." (PMID 23536873, 2013). "Our study provides two novel findings that HDGF promotes melanoma progression in both human and mouse melanoma cells and it encourages cell invasion and metastasis in a mouse model of melanoma." (PMID 23536873, 2013). "Our finding reveals that E-cadherin protein level is down-regulated, whereas vimentin and α-SMA are up-regulated in HDGF-treated melanoma cells." (PMID 23536873, 2013). "In summary, we presented evidences that HDGF promotes melanoma progression through the activation of tumorigenesis, angiogenesis and metastasis." (PMID 23536873, 2013). "It was found that HDGF shRNA-transduced melanoma cells significantly reduced colony formation and such responses were potentiated by HDGF overexpression, implicating a role of HDGF in anchorage-independent growth." (PMID 23536873, 2013). "One possibility is that HDGF facilitates EMT in melanoma, thereby creating a niche environment for metastasis." (PMID 23536873, 2013). "To investigate the correlation of HDGF expression with tumor progression, we assessed the effects of HDGF inhibition on melanoma using small interfering RNA (shRNA) in human A375 and A2058 melanoma cells." (PMID 23536873, 2013). "An application of rHDGF (10 ng/mL) for 7–10 days increased colony formation, whereas HDGF shRNA gene delivery significantly inhibited colony-forming capability in both A375 and A2058 melanoma cells." (PMID 23536873, 2013). "HDGF overexpression is correlated with poor prognosis in various types of cancer including melanoma." (PMID 23536873, 2013). "Histological analysis of excised tumors revealed higher degree of cell proliferation and neovascularization in HDGF-overexpressing melanoma." (PMID 23536873, 2013). "However, the underlying mechanism of HDGF overexpression in developing melanoma remains unclear." (PMID 23536873, 2013). "Knocking down HDGF with HDGF shRNA demonstrates a significant inhibition of tumor growth and retards lung metastasis by reducing tumor invasion and colonization in established melanoma." (PMID 23536873, 2013). "To evaluate the effect of HDGF expression on melanoma growth in vivo, we employed the B16–F10 syngeneic melanoma models." (PMID 23536873, 2013). "Two proteins, nuclophosmin/B23 and hepatoma-derived growth factor (HDGF), were strongly upregulated in melanoma, while cathepsin D was downregulated in melanoma cell lines." (PMID 22084682, 2011). "We first confirmed that an infection of B16–F10 melanoma cells with shRNA (Ad-HDGF shRNA) targeting HDGF could silence HDGF expression and Ad-HDGF increased HDGF expression." (PMID 23536873, 2013).
melanoma (continued). "Exogenous application of HDGF stimulated colony formation and invasion of human melanoma cells." (PMID 23536873, 2013). "Therefore HDGF has both mitogenic and proangiogenic activities that renders it a favourable therapeutic target for the treatment of melanoma." (PMID 23536873, 2013). "Moreover, HDGF overexpression stimulated the degree of invasion and colony formation of B16–F10 melanoma cells whereas HDGF knockdown exerted opposite effects in vitro." (PMID 23536873, 2013). "Moreover, the expression of HDGF correlates with tumor progression and the frequency of HDGF expression increases from benign nevi to late stages of melanoma." (PMID 23536873, 2013). "The present study provides evidence that HDGF promotes tumor progression of melanoma and targeting HDGF may constitute a novel strategy for the treatment of melanoma." (PMID 23536873, 2013). "The results from exogenous application of HDGF and genetic modulation of HDGF in the present study support such notion that HDGF elevation promotes the neoplastic transformation in melanocytes and HDGF expression regulates the melanoma progression." (PMID 23536873, 2013). "Therefore, expression of HDGF appears to correlate with melanoma malignant behaviours such as proliferation and invasion, but not to the oncogenic transformation potentials of melanocytes." (PMID 23536873, 2013). "To evaluate whether HDGF contributes to the regulation of metastasis in melanoma, we first investigated the extent of invasion of B16–F10 melanoma cells after HDGF known down or overexpression in vitro." (PMID 23536873, 2013). "Our study showed that HDGF promoted melanoma progression in both human and mouse melanoma cells." (PMID 23536873, 2013). "Since HDGF is a well-known pro-angiogenic factor, HDGF may promote tumor progression through the modulation of angiogenesis in melanoma." (PMID 23536873, 2013). "HDGF appears to be an important growth factor for melanoma growth and its expression could be shuttled between cytoplasm and nucleus under different conditions such as cell proliferation cycle and state of differentiation." (PMID 23536873, 2013). "Furthermore, up-regulation of HDGF has been shown in a human melanoma cell line and clinical specimen of melanoma." (PMID 23536873, 2013). "Indeed, our data showed that exogenous HDGF application stimulates the capacity of colony formation and invasion of human melanoma cells." (PMID 23536873, 2013). "Conversely, an overexpression of HDGF increased vessel formation in melanoma." (PMID 23536873, 2013). "In addition, by employing the syngeneic B16–F10 melanoma models, overexpression or knockdown of HDGF influenced the tumor progression such as tumor growth and metastasis in mice." (PMID 23536873, 2013). "Furthermore, a correlation between the degree of HDGF overexpression and the course of disease was found for some types of cancer, including melanoma, leading to the classification of HDGF as a novel prognostic marker." (PMID 22014102, 2011). "In addition, HDGF-expression was graded with progression, suggesting that the frequency of HDGF-expression increases from benign nevi gradually to late melanoma stages." (PMID 22014102, 2011). "Heparan-sulfate proteoglycans (HPSE) digestion-generated heparan sulfate fragments of about 10 kDa in B16B15b melanoma cell stimulated melanoma migration and angiogenesis, which were possibly due to signaling by some other unknown heparin-binding growth factor(s)." (PMID 37389120, 2023). "Targeting HDGF may have therapeutic potential for melanoma therapy." (PMID 23536873, 2013). "Our findings indicate that targeting HDGF may have therapeutic potential for melanoma therapy." (PMID 23536873, 2013). "Thus, we evaluated whether HDGF affected the EMT of melanoma cells by examining the expression of EMT marker molecules." (PMID 23536873, 2013).
melanoma (continued). "Conversely, Ad-HDGF shRNA infection potentiated protein level and the promoter activity of E-cadherin, and reduced the protein levels of vimentin and α-SMA in B16–F10 melanoma cells." (PMID 23536873, 2013). "In this study, human melanoma cell lines (A375, A2058, MEL-RM and MM200) showed higher levels of HDGF gene expression, whereas human epidermal melanocytes (HEMn) expressed less." (PMID 23536873, 2013). "We also show that HDGF modulates EMT changes by down-regulating E-cadherin and up-regulating vimentin and α-SMA, which contributes to tumor cell invasion and metastasis in melanoma in vitro and in vivo." (PMID 23536873, 2013). "Because the reciprocal regulation between HDGF and TGFβ exists during liver fibrosis, it is plausible that HDGF might induce TGFβ up-regulation and concomitantly promote EMT during melanoma progression." (PMID 23536873, 2013). "Therefore, HDGF may regulate EMT process and cytoskeletal remodelling for triggering metastasis of melanoma." (PMID 23536873, 2013). "Similarly, HDGF overexpression by Ad-HDGF gene delivery reduced the protein level and promoter activity of E-cadherin, while it elevated the protein levels of vimentin and α-SMA in B16–F10 melanoma cells." (PMID 23536873, 2013). "We chose to target the HDGF expression to melanocytes with the help of a Tyrosinase promoter/enhancer element since results presented by Bernard and co-workers revealed HDGF-expression in melanomas whereas HDGF was absent or weakly present in nontumorigenetic melanocytes." (PMID 22014102, 2011). "Although, HDGF-/-/Ink4a+/- mice displayed an increased number of epidermoid cysts after exposure to UV light, no melanomas or premelanocytic alterations could be detected in this mouse model." (PMID 22014102, 2011). "However, Western blot analysis of primary melanocyte lysates revealed that wildtype melanocytes express no substantial amount of HDGF, whereas HDGF could be detected in B16F10 mouse melanoma cell lysate." (PMID 22014102, 2011).